ADA (adenosine deaminase)
Diseases named in the same sentence as ADA in open-access papers (continued):
Sharing a sentence is not in itself a finding about the gene and the disease.
severe combined immunodeficiency (continued). "Adenosine deaminase deficiency (ADA) is an autosomal recessive disorder leading to severe combined immunodeficiency (SCID)." (PMID 37208598, 2023). "Consider the case of adenosine deaminase (ADA)-deficient severe combined immunodeficiency (SCID), a very rare congenital disorder of the immune system." (PMID 36778019, 2023). "In 1990, the United States Food and Drug Administration (FDA) approved Adagen (pegademase bovine), the world’s first PEGylated drug, for the treatment of severe combined immunodeficiency disease (SCID) associated with a deficiency of adenosine deaminase." (PMID 37177365, 2023). "For treatment of severe combined immunodeficiency caused by adenosine deaminase deficiency (ADA-SCID), these issues were resolved one by one leading to evidence of immunological reconstitution in patients." (PMID 36209077, 2022). "Deficiency of adenosine deaminase (ADA) manifests as severe combined immunodeficiency (SCID), caused by accumulation of toxic purine degradation by-products." (PMID 36685585, 2022). "Adenosine deaminase (ADA) deficiency is a rare inherited disorder of purine metabolism leading to life threatening severe combined immunodeficiency (SCID), otherwise known as ADA-SCID." (PMID 36685585, 2022). "Adenosine deaminase (ADA) deficiency is an inborn error of metabolism caused by a mutation in the ADA gene and results in a severe combined immunodeficiency (ADA-SCID) and other system manifestations." (PMID 33738330, 2021). "Gene therapy has successfully treated several PIDs including Adenosine Deaminase Severe Combined Immunodeficiency (SCID), X-linked SCID, Artemis SCID, Wiskott-Aldrich Syndrome, X-linked Chronic Granulomatous Disease and Leukocyte Adhesion Deficiency-I." (PMID 33717203, 2021). "Autosomal recessive inherited defects that profoundly compromise ADA enzyme activity cause severe combined immunodeficiency (ADA-SCID) with increased susceptibility to infections, autoimmunity, and malignancy." (PMID 34777360, 2021). "ADA deficiency causes early-onset severe combined immunodeficiency (SCID), which is characterized by the loss of functional T, B, and NK cells, impaired cellular and humoral immunity, and susceptibility to infections." (PMID 34885056, 2021). "One of the first reports of a PID patient-derived iPSC line was from a patient with an adenosine deaminase (ADA) deficit, which causes severe combined immunodeficiency (ADA-SCID)." (PMID 33109263, 2020). "Gene therapy had driven fantastic hope in the mid-1990s when addressing severe combined immunodeficiency (SCID) due to deficiency of the enzyme adenosine deaminase (ADA-SCID)." (PMID 33554501, 2020). "Adenosine deaminase-deficient severe combined immunodeficiency disease (ADA-SCID) is a primary immune deficiency characterized by mutations in the ADA gene resulting in accumulation of toxic compounds affecting multiple districts." (PMID 29456531, 2018). "Extreme dysfunction in purinergic metabolism can additionally manifest in ADO deaminase-severe combined immunodeficiency (ADA-SCID), caused by accumulation of ADO due to ADA loss of function, ultimately resulting in partial or complete lymphopenia." (PMID 30425720, 2018). "This is highly successful, as corroborated by recent regulatory approvals for adenosine deaminase (ADA)‐deficient severe combined immunodeficiency (SCID), and can provide a life-long cure for patients that cannot be treated with bone marrow transplantation." (PMID 30067117, 2018).
severe combined immunodeficiency (continued). "Extreme dysfunction in purinergic metabolism can lead to adenosine deaminase-severe combined immunodeficiency (ADA-SCID), which causes the accumulation of adenosine due to ADA loss of function, ultimately resulting in partial or complete lymphopenia." (PMID 30467503, 2018). "Adenosine Deaminase (ADA) deficiency is an autosomal recessive variant of severe combined immunodeficiency (SCID) caused by systemic accumulation of ADA substrates." (PMID 28074903, 2017). "Mutations in the adenosine deaminase (ADA) gene are among the most common causes for severe combined immunodeficiency (SCID)." (PMID 28074903, 2017). "HSC gene therapy has been used to successfully treat monogenic diseases including adenosine deaminase deficient-severe combined immunodeficiency (ADA-SCID), X-linked SCID, X-linked adrenoleukodystrophy and hemophilia B." (PMID 28536375, 2016). "Lymphocyte maturation and function is particularly affected and, hence, deficiency of ADA leads to a severe combined immunodeficiency (SCID)." (PMID 27579027, 2016). "Adenosine deaminase (ADA) deficiency is best known as a form of severe combined immunodeficiency (SCID) that results from mutations in the gene encoding ADA." (PMID 27579027, 2016). "It is assumed that ADA plays a crucial role in development of the immune system, while its innate deficiency causes severe combined immunodeficiency (SCID)." (PMID 24887139, 2014). "2′-Deoxyadenosine behaves as a cytotoxic metabolite and is generally considered the primary cause of lymphotoxicity in ADA-severe combined immunodeficiency (SCID; Hirschhorn and Candotti, 2006)." (PMID 22969765, 2012). "MLV-derived vectors have been used with success to achieve sustained correction of two forms of severe combined immunodeficiency (SCID)—SCID-X1 (Gamma-c deficiency) and adenosine deaminase deficiency." (PMID 15696201, 2005). "Examples include, Strimvelis, the first stem-cell based gene therapy, an autologous CD34+ HSC product with wildtype adenosine deaminase (ADA) sequence introduced by a ɣ-retroviral vector for the treatment of ADA-severe combined immunodeficiency." (PMID 40704043, 2025). "In 1990, gene therapy was first applied clinically in a trial treating two children with Adenosine-deficient Severe Combined Immunodeficiency (ADA-SCID), using retroviral vectors to introduce the ADA gene into their T cells." (PMID 41300975, 2025). "Interestingly, the same vector used in a different condition, namely the adenosine deaminase deficient severe combined immunodeficiency (ADA-SCID), was very successful in providing benefit to patients." (PMID 39000440, 2024). "Adenosine deaminase (ADA) deficiency, an autosomal recessive variant, is the second most common form of severe combined immunodeficiency (SCID)." (PMID 38711702, 2024). "The most extreme syndrome of lymphocyte dysfunction, severe combined immunodeficiency (SCID), arises from mutations in a number of genes: IL2RG, RAG1, RAG2, ADA, JAK3, and IL7RG." (PMID 36839582, 2023). "Adenosine deaminase‐severe combined immunodeficiency is another common form and one of the most damaging." (PMID 37177842, 2023). "However, adenosine deaminase deficient severe combined immunodeficiency (ADA-SCID) seems to differ from other inherited immunodeficiencies, as insertional oncogenesis is rare after γRV treatment." (PMID 36992407, 2023). "In the context of inborn errors of immunity, HIS occurrence has been reported in severe combined immunodeficiency (SCID) patients, including two cases of adenosine deaminase deficient-SCID (ADA-SCID)." (PMID 37435083, 2023). "ADA deficiency leads to an accumulation of toxic purine degradation by-products, primarily affecting lymphocytes, leading to severe combined immunodeficiency (SCID) caused by adenosine deaminase deficiency." (PMID 37794048, 2023).
severe combined immunodeficiency (continued). "The first successful attempt of gene therapy using autologous HSCT was performed using gamma retroviral vectors (RVs) in X-linked severe combined immunodeficiency (SCID-X1) and adenosine deaminase deficiency (ADA-SCID)." (PMID 36698790, 2022). "In 1990, the first clinical trial of gene-modified T cells used RV-mediated transfer of adenosine deaminase (ADA) for treatment of two children with severe combined immunodeficiency (ADA-SCID)." (PMID 35784280, 2022). "This provides severe immunosuppressive effects observed, for instance, in severe combined immunodeficiency (SCID) patients, who have deficient ADA activity." (PMID 36204140, 2022). "NeoBaseTM 2 tests for more than 50 analytes, including the markers of adenosine deaminase severe combined immunodeficiency (ADA-SCID) and X-linked adrenoleukodystrophy (X-ALD), following a fast extraction procedure that allows also for the yield of diketones (e.g., succinylacetone)." (PMID 34436414, 2021). "A new approach is adopted to treat primary immunodeficiency disorders, such as the severe combined immunodeficiency (SCID; e.g., adenosine deaminase SCID [ADA-SCID] and IL-2 receptor X-linked severe combined immunodeficiency [SCID-X1])." (PMID 33987480, 2021). "A typical instance includes the severe combined immunodeficiency ([SCID] e.g., adenosine deaminase SCID [ADA-SCID] and IL-2 receptor X-linked severe combined immunodeficiency [SCID-X1])." (PMID 33987480, 2021). "EFS-ADA is a 4-kb LV for treating ADA severe combined immunodeficiency (ADA-SCID) that is capable of high-level and consistent ADA gene transfer and expression." (PMID 33186538, 2021). "Adenosine deaminase-deficient severe combined immunodeficiency (ADA-SCID) is a primary immunodeficiency characterized by severe pan-lymphopenia (T−, B− and NK−), severe and recurrent infections, failure to thrive and death in the first year of life, if left untreated." (PMID 34853379, 2021). "The first clinical trial of gene therapy in children with severe ADA-associated combination immunodeficiency (ADA ID SCID) was injected with T cells, which have shown a modification in the ADA gene." (PMID 34207502, 2021). "This possible therapeutic approach is possible because PEGylated ADA is an FDA-approved drug (Pegademase bovine) for use in people with severe combined immunodeficiency disease and recombinant ADA has been proposed as an effective adjuvant with HIV-1 vaccines." (PMID 33324223, 2020). "The first ex vivo stem cell-based therapy to receive regulatory approval, Strimvelis, treats the rare congenital disease adenosine deaminase severe combined immunodeficiency (ADA-SCID)." (PMID 32637403, 2020). "CD34-positive cells from ADA-severe combined immunodeficiency patients transferred with the ADA gene with virus ex vivo are transplanted to refill ADA." (PMID 33425872, 2020). "ADA deficiency is associated with severe combined immunodeficiency (SCID)." (PMID 32739778, 2020). "First clinical trials performed with gamma retroviral vectors for adenosine deaminase severe combined immunodeficiency (ADA-SCID), X-linked SCID (SCID-X1), and Wiskott-Aldrich syndrome (WAS) identified that gene therapy is a valid therapeutic option in patients without an HLA-identical donor." (PMID 28523402, 2017). "In 2016, the European Commission granted market approval to GlaxoSmithKline (GSK) for ex vivo hematopoietic stem cell (HSC) gene therapy for the treatment of adenosine deaminase (ADA)‐deficient severe combined immunodeficiency (SCID), a very rare congenital disorder of the immune system." (PMID 28396566, 2017).
severe combined immunodeficiency (continued). "In that protocol, two patients with severe combined immunodeficiency (SCID) due to adenosine deaminase (ADA) deficiency were treated with a retroviral vector carrying the ADA coding sequence under the transcriptional control of the promoter/enhancers of the long terminal repeat of the MLV." (PMID 27729044, 2016). "Deficiency in ADA causes severe combined immunodeficiency disease (SCID)." (PMID 25861755, 2015). "Gene modifications of HSCs show promise to treat diseases like ADA SCID (adenosine deaminase severe combined immunodeficiency disease) and gene-modified MSCs are just entering the first clinical trials for indications such as advanced adenocarcinoma." (PMID 26416686, 2015). "This technique was first employed successfully in 1990 when it was used to treat severe combined immunodeficiency (SCID), a disease resulting from a deficiency of the enzyme adenosine deaminase." (PMID 12875045, 2002). "ADA deficiency can be further classified as early-onset (i.e. infants and small children) ADA-SCID; or less severe delayed (i.e. usually diagnosed between 1 and 10 years), or late-onset (i.e. diagnosed between 2nd to 4th decades) combined immunodeficiency (ADA-CID)." (PMID 40140214, 2025). "In addition, there is a report of delayed onset T-cell leukaemia in a child treated for adenosine deaminase severe combined immunodeficiency (ADA-SCID) using Strimvelis®, the first γRV-gene therapy licensed in Europe." (PMID 40200078, 2025). "ADA deficiency is a severe combined immunodeficiency (SCID), otherwise known as ADA-SCID." (PMID 41226098, 2025). "Similar retroviral and lentiviral technology can be applied to autologous haematopoietic stem cells, exemplified by Strimvelis and Zynteglo, licenced treatments for adenosine deaminase‐severe combined immunodeficiency (ADA‐SCID) and β‐thalassaemia respectively." (PMID 37177842, 2023). "Both recombinant ADA protein and the viral vectored ADA gene are approved in enzyme replacement therapy (ERT) for the treatment of adenosine deaminase deficiency-based severe combined immunodeficiency (SCID), representing an excellent precedent for a favorable safety profile of the ADA enzyme." (PMID 34948316, 2021). "Reversion mutations and resultant mosaicism have been reported in Bloom syndrome, X-linked and adenosine deaminase severe combined immunodeficiency (X-SCID and ADA-SCID), Diamond Blackfan anemia (DBA), Wiskott-Aldrich syndrome, epidermolysis bullosa, tyrosinemia, and dyskeratosis congenita (DC)." (PMID 32065290, 2020). "Despite relying on an early γ‐retroviral vector design, HSC GT for one type of PID, Adenosine Deaminase Severe Combined Immunodeficiency (ADA‐SCID), has uniquely and consistently proven safe and has become the first ex vivo GT drug now available on the EU market." (PMID 30670463, 2019). "Adenosine deaminase (ADA) deficiency leads to an accumulation of toxic purine degradation by-products, most potently affecting lymphocytes, leading to adenosine deaminase-deficient severe combined immunodeficiency." (PMID 29690908, 2018). "Deficient ADA enzyme has reduced ability to convert deoxyadenosine to non-toxic metabolites causing eventually severe combined immunodeficiency (SCID)." (PMID 33072949, 2018). "Adenosine deaminase (ADA) is a key enzyme of the purine salvage pathways and deficiency caused by mutations in the ADA gene results in one of the more common causes of autosomal recessive severe combined immunodeficiency (SCID), accounting for approximately 10–15% of cases in outbred populations." (PMID 29690908, 2018). "The simple idea of gene replacement, by delivering a functional copy of the mutated gene, seems to be the answer to a wide variety of genetic disorders, such as muscular dystrophy, phenylketonuria or adenosine deaminase severe combined immunodeficiency (ADA-SCID)." (PMID 24549268, 2014).
severe combined immunodeficiency (continued). "Gene therapy is a very promising treatment for adenosine deaminase severe combined immunodeficiency (ADA-SCID), not only because the nature of the disorder makes the patient less likely to reject the vector, but also because it is a well characterized monogenic disorder." (PMID 20042112, 2009). "In 1990, Anderson carried out the first-ever clinical trial for gene therapy, utilizing a murine retroviral vector to introduce the adenosine deaminase (ADA) gene into T cells of children with severe combined immunodeficiency (SCID)." (PMID 40227707, 2025). "Related to adenosine deaminase-severe combined immunodeficiency (ADA-SCID), the defected adenosine deaminase (ADA) gene has been replaced by delivery with SIN-γRV or SIN-LV vectors." (PMID 36992407, 2023). "Gene therapy was first approved for a human trial in the United States in 1990 to target genetic defects in adenosine deaminase severe combined immunodeficiency (ADA-SCID)." (PMID 37601627, 2023). "The first viral-mediated gene therapy was approved for clinical use in 1990 for adenosine deaminase-severe combined immunodeficiency (ADA-SCID)." (PMID 35892690, 2022). "ADA and PNP deficiency causes severe combined immunodeficiency (SCID) with loss of T and B lymphocytes." (PMID 34986329, 2022). "Mutations in genes that affect the development or function of T and B cells [DCLRE1C(ARTEMIS), ZAP70, RAG1/2, IL2RG, ILRA7, LIG4, JAK3, ADA] can result in intestinal inflammation along with recurrent infections from severe combined immunodeficiency (SCID)." (PMID 34122435, 2021). "Deficiency of adenosine deaminase (ADA, EC3.5.4.4), a housekeeping enzyme intrinsic to the purine salvage pathway, leads to severe combined immunodeficiency (SCID) both in humans and mice." (PMID 34853379, 2021). "The first of this class of products, Strimvelis®, received marketing authorization in Europe in 2016 for the treatment of patients with severe combined immunodeficiency caused by adenosine deaminase deficiency (ADA-SCID) lacking an HLA-matched related stem cell donor." (PMID 34452394, 2021). "ADA (adenosine deaminase) encodes a protein which is important for purine metabolism, and ADA deficiency causes severe combined immunodeficiency (SCID)." (PMID 34680906, 2021). "The inclusion of ADA-SCID (adenosine deaminase-severe combined immunodeficiency) in expanded newborn screening by tandem mass spectrometry, as well as the expansion of the NBS programs to include lysosomal storage disorders (LSDS), could be the second target to achieve." (PMID 33072938, 2018). "The two major ADA isoforms are ADA1, whose deficiency is cause of a severe combined immunodeficiency (SCID), and ADA2." (PMID 27609179, 2016). "Early promising results on the treatment of adenosine deaminase-severe combined immunodeficiency (ADA-SCID) by using gene therapy in the early 1990s led the scientific community to apply the same principle to a host of other diseases, including HIV/AIDS." (PMID 17300725, 2007). "It is known that ADA-deficient patients present with typical early-onset severe combined immunodeficiency (ADA-SCID), which may be accompanied by neurologic or behavioral abnormalities." (PMID 40710358, 2025). "Different mutations have been reported in this particular gene and are associated with human disorders characterized by compromised immune function, including severe combined immunodeficiency disease (SCID), a condition caused by a lack of adenosine deaminase." (PMID 39546272, 2025).